INS (insulin)
Diseases named in the same sentence as INS in open-access papers (continued):
Sharing a sentence is not in itself a finding about the gene and the disease.
diabetes (continued). "Diabetes self-management focuses on food and insulin administration, which may contribute to development of EDs." (PMID 41484931, 2026). "Epidemiological studies have reported that higher circulating n-6 PUFAs, particularly arachidonic acid (ARA), are associated with greater adiposity and risk of diabetes, whereas higher n-3 PUFAs (EPA and DHA) are linked to improved insulin sensitivity and lower body fat." (PMID 41499450, 2026). "A study in Scotland used C-peptide as an indicator of retained secretory capacity where T1D had been diagnosed initially, enabling re-categorization to T2D or monogenic diabetes, discontinuation of insulin therapy and provision of more appropriate antidiabetic therapy." (PMID 41355468, 2026). "Notably, 95% of these episodes occurred prior to the introduction of modern insulin analogs, which have since redefined contemporary diabetes therapy." (PMID 41596449, 2026). "The identification of biallelic variants among individuals diagnosed with diabetes in adolescence and individuals with non-insulin-treated diabetes has implications for treatment and genetic testing and indicates that inclusion of ZNF808 to genetic testing panels used for MODY should be considered." (PMID 41500078, 2026). "C-peptide is a useful biochemical measure for assessing pancreatic β-cell function, and it may be used to both classify the type of diabetes and to predict insulin requirement." (PMID 41494166, 2026). "After adjustment for age, gender, social deprivation score, diabetes duration, HbA1c, insulin administration mode, BMI, smoking status and physical activity, an association was observed between EQ5D‐VAS and severity of complications (DCSI), regardless of the model used." (PMID 41328549, 2026). "Finally, fractional-order diabetes models incorporating insulin therapy and awareness controls have been developed to optimize treatment strategies." (PMID 41544184, 2026). "Diabetes is a chronic inflammatory disease due to decreased insulin release or insulin resistance." (PMID 41750302, 2026). "Finally, the APAC consensus recommends CGM in all patients with diabetes using intensive insulin regimens, either as continuous or intermittent use." (PMID 41601933, 2026). "Unlike channelopathies, diabetes caused by β-cell destruction has traditionally been considered irreversible, requiring lifelong insulin therapy." (PMID 41614934, 2026). "Even in patients with type 2 diabetes mellitus in the DK/DKA group, a positive correlation was seen between plasma glucagon and serum CPR levels, similar to HHS, and the possibility was suggested that α cell insulin resistance is a cause of hyperglucagonemia." (PMID 41292690, 2026). "Future study may involve expanding the BPA to include other types of diabetes medications besides insulin, and the potential to expand this initiative to other centers." (PMID 41551323, 2026). "Type 2 diabetes mellitus (T2DM) is a multifaceted metabolic disorder marked by impaired insulin action, pancreatic β-cell dysfunction, and the involvement of several interconnected mechanisms, including inflammation, oxidative stress, and epigenetic alterations." (PMID 41599220, 2026). "In addition, factors such as lipotoxicity, defects in the incretin system, hyperglucagonemia, increased renal glucose reabsorption, and central insulin resistance contribute to the progression of diabetes." (PMID 41549124, 2026). "Patients with diabetes (excluding type 1 diabetes mellitus) scheduled for elective surgery were randomly assigned to the closed-loop group (open-source hybrid closed-loop AID system) or the control group (conventional insulin pump)." (PMID 42193423, 2026). "Additionally, protecting the encapsulated biomaterial capsules can provide a controlled release of therapeutic agents, such as insulin or growth factors, which are essential for treating chronic conditions like diabetes and cancer." (PMID 41216376, 2026).
diabetes (continued). "The presence of clinically relevant type 2 diabetes mellitus was evaluated preoperatively and on follow-up, defined as whether patients actively required other antidiabetic medication or insulin." (PMID 41583359, 2026). "Also, it was found that patients who use insulin have lower diabetes knowledge than those using OHAs only." (PMID 41311517, 2026). "However, diminished brain insulin sensitivity in obesity, diabetes, and dementia has sparked interest in the impact of insulin resistance in brain and periphery on brain metabolism and function." (PMID 39185744, 2025). "These include age, alcohol use disorder, cerebrovascular disease, inpatient hospitalizations, Medicaid coverage, BMI coefficient of variation, hearing loss, emergency room visits and hospital observations, BMI, diastolic blood pressure, diabetes, and insulin use." (PMID 40034839, 2025). "We note the consistent relationship between a higher MDS with increased risks of outcomes known to be associated with low magnesium intake and/or status, such as CVD and hypertension, CKD and impaired kidney function, diabetes and glucose–insulin dynamics, and related biomarkers." (PMID 41156538, 2025). "In adults without diagnosed diabetes, total white potato intake was positively associated with glucose, insulin, Homeostatic Model Assessment for Insulin Resistance and waist circumference." (PMID 41457584, 2025). "Consensus was reached on 114 items, resulting in a finalized self-assessment tool organized into eight sections covering medicine groups such as insulin and oral diabetes medicines, anticoagulants, opioids, immunosuppressants, methotrexate, and over-the-counter high-alert medications." (PMID 41142511, 2025). "In this study, we employed MeRIP-seq and RNA-seq to uncover that the intersection genes of differential genes in m6A modification sites and differential mRNAs predominantly contribute to metabolic pathways in people with diabetes before and after intensive insulin therapy." (PMID 40299682, 2025). "As for her treatment course, the patient received insulin for type 2 diabetes mellitus." (PMID 41589173, 2025). "The discovery of insulin in 1921 represented a milestone in the treatment of diabetes [...]." (PMID 41007769, 2025). "However, these three low amber range SMBG values represent only 0.1% of all recorded in-flight SMBG values, equivalent to one low amber reading in every 360 flights made by a pilot with insulin-treated diabetes." (PMID 39496965, 2025). "In diabetes, insulin function is impaired, leading to reduced glucose uptake by the muscles." (PMID 41464593, 2025). "A clearer understanding of the insulin–bone axis may guide the development of targeted strategies to mitigate skeletal complications in individuals with diabetes mellitus." (PMID 40564223, 2025). "Diabetes is a condition characterized by elevated blood glucose levels, resulting from insufficient insulin production by the pancreas or impaired cellular response to insulin." (PMID 40705152, 2025). "Moreover, we observed an almost significant positive association between diabetes mellitus and high expression of CNOT7; this result is consistent with a previous study stating that CNOT7 knockdown enhanced insulin sensitivity and glucose clearance." (PMID 40806280, 2025). "In other words, even if genetic PAM deficiency causes sarcopenia in the nondiabetic population, it seems plausible that long-term reduction of insulin secretion is the prime consequence of genetic PAM deficiency, causing an increase in the risk of diabetes and sarcopenia." (PMID 39137152, 2025). "SFP fraction can ameliorate the pathogenesis of diabetes mellitus through a variety of mechanisms, such as increasing insulin sensitivity, stimulating insulin secretion from pancreatic β-cells, promoting glucose uptake and metabolism, and improving the efficiency of glucose metabolism." (PMID 40137284, 2025).
diabetes (continued). "In other words, regardless of the underlying cause of diabetes onset, zinc status tends to deteriorate in affected individuals, yet higher zinc levels within this group are associated with better insulin sensitivity." (PMID 41439937, 2025). "The rate of insulin use was 88.4%, indicating a high rate of insulin therapy in the diabetes group." (PMID 40106491, 2025). "An mRNA approach to diabetes could potentially provide more physiological and long-lasting glycemic control by enabling the patient's own cells to produce insulin in a controlled manner." (PMID 41438702, 2025). "Even in men without diabetes, medium‐chain acylcarnitines are inversely associated with insulin sensitivity." (PMID 40289598, 2025). "We advise patients to eat more foods rich in high protein postoperatively, and sweets such as sugar and beverages are strongly discouraged foods because eating sweets can cause patients to regain weight, as well as being detrimental to diabetes and insulin resistance controlling." (PMID 41393940, 2025). "However, the majority of them (93%) were aware that the major hormone playing a role in diabetes was insulin." (PMID 40019907, 2025). "Overall, these studies have highlighted the value of connected insulin pens to confirm that insulin boluses are administered, as well as allowing the person with diabetes and their healthcare provider to regularly review and adjust their insulin dosing and/or food intake appropriately." (PMID 41039947, 2025). "The use of CGM systems in PD patients with diabetes might be of great help in adjusting insulin treatment to glucose influx from glucose-containing PD solution, thereby maintaining stable blood glucose without episodes of hypoglycemia." (PMID 40430224, 2025). "This dysfunction may play a more significant role than insulin resistance itself in the eventual progression to diabetes in these patients." (PMID 41018201, 2025). "The future of diabetes management lies in the evolution of fully closed-loop systems which may need to be paired with adjunctive medications and enhanced insulin delivery methods that facilitate faster absorption." (PMID 40231429, 2025). "NSAIDs may offer metabolic advantages, such as reducing systemic inflammation and improving insulin sensitivity, which could help in diabetes prevention or management." (PMID 40866832, 2025). "Through microbiota-mediated pathways, including SCFA production, metabolite transformation, gut barrier reinforcement, and immune modulation, antioxidants exert profound effects on insulin sensitivity, inflammation, and glycemic control in type 2 diabetes mellitus." (PMID 40563357, 2025). "Her diabetes medications include metformin and insulin and her HbA1c values have remained ≤7.5%." (PMID 40439123, 2025). "Six patients have diabetes; five are taking insulin; and the sixth patient is taking metformin." (PMID 41156718, 2025). "As many factors such as the type and duration of diabetes, insulin requirement, presence of complications, and poor glycemic control can influence the development of PEI in diabetic patients, the frequency of PEI in diabetic patients varies despite being more common than in the general population." (PMID 40521801, 2025). "Over recent decades, advancements in diabetes management, including improved insulin therapies, continuous glucose monitoring, and multidisciplinary care approaches, have contributed to extended life expectancy in individuals with T1D and type 2 diabetes (T2D)." (PMID 41323965, 2025). "The insulin/IGF-1 signaling is implicated in regulating fetal growth, T-cell maturation, linear growth, and the development of conditions such as acne, atherosclerosis, diabetes mellitus, obesity, and cancer." (PMID 40357063, 2025). "Physical health is sort of more acute, for example when a patient with diabetes needs insulin." (PMID 40241331, 2025).
diabetes (continued). "Additionally, the ability of these compounds to enhance insulin sensitivity, regulate blood glucose levels, and improve overall metabolic health further underscores the promising role of phenolic compounds in diabetes therapy." (PMID 41150789, 2025). "Consequently, the empagliflozin group included patients with poorer glycemic control, longer diabetes duration, insulin use, and coexisting chronic complications such as cardiovascular diseases." (PMID 40731782, 2025). "Diabetes medication has advanced substantially since the successful isolation of insulin in 1921." (PMID 39453501, 2025). "Similarly, camel milk has demonstrated clinical efficacy in diabetes management, with studies indicating 30–35% reductions in insulin requirements among patients." (PMID 40722905, 2025). "Liver transplant recipients with a history of diabetes can be categorised into three groups: those with undiagnosed diabetes (HbA1c > 6.5%) or treatment‐naive individuals, those with a history of insulin therapy, and those with a history of oral antidiabetic medication use." (PMID 40931439, 2025). "Fourth, the binary classification of responders may oversimplify patient heterogeneity, as participants likely varied in diabetes duration, insulin sensitivity, and medication history, potentially confounding miRNA associations." (PMID 40806035, 2025). "Both types of diabetes cause an increase in blood glucose levels, either due to lack of insulin or insulin resistance." (PMID 41373306, 2025). "In total, 83 (39.9 %) patients with diabetes were treated with insulin." (PMID 40687396, 2025). "By improving insulin signaling, chromium facilitates cellular glucose uptake and may reduce oxidative stress in diabetes." (PMID 41170369, 2025). "Similarly, it was debated if people with diabetes were capable of blood glucose self-monitoring in the 1970s, calculating their insulin doses by themselves, or understanding real-time readings of their CGM device —all aspects that are standard of care today." (PMID 39761553, 2025). "By highlighting these systemic and psycho-social factors, we underscore the need for reforms that extend beyond insulin provision to a more inclusive model of diabetes care, one that acknowledges local realities and bolsters support for patients and caregivers alike." (PMID 40938912, 2025). "The most common type of diabetes is type 2-diabetes which accounts for over 90% of all diabetes worldwide, and occurs when body became resistant to insulin (i.e., inability of body cell’s to respond fully to insulin) or when pancreatic beta cells failed to produce enough amounts of insulin." (PMID 39995414, 2025). "This review discusses the peculiarities of diabetes associated with WS1 and the reproductive outcomes in WS1, reporting a case of successful pregnancy in a woman with WS1 treated with a hybrid closed-loop insulin pump." (PMID 40988749, 2025). "Since the introduction of the first closed-loop system in the 1960s and 1970s, advancements in diabetes management have been closely tied to innovations in diabetes technology, particularly the widespread adoption of continuous insulin delivery systems and glucose monitoring devices." (PMID 40465596, 2025). "Furthermore, this study was retrospective, and some information were not available, most importantly the presence of diabetic kidney disease, duration of diabetes, glycemic control, insulin resistance, and drug classes, precluding adjustment for these factors." (PMID 41331616, 2025). "The increasingly impaired glycemic control in Omani patients on oral agents, as well as insulin, might be an indicator of a more advanced stage of diabetes or greater insulin resistance." (PMID 40786180, 2025). "Therefore, comprehensive educational programs are essential for diabetes care, empowering patients to manage their condition effectively, bridging knowledge gaps, and enhancing insulin therapy outcomes." (PMID 40226177, 2025).
diabetes (continued). "Diabetes mellitus (DM) is a metabolic disorder that primarily affects carbohydrate, lipid, and protein metabolism, especially glucose processing, due to either insufficient insulin production or decreased tissue sensitivity to insulin." (PMID 40732988, 2025). "Younger age, a shorter duration of diabetes, and the absence of insulin therapy are associated with a higher likelihood of complete remission." (PMID 39715944, 2025). "Furthermore, vitamin D intake has been shown to influence insulin resistance positively and correlates with insulin secretion in patients with type 2 diabetes mellitus." (PMID 39935579, 2025). "In cancer treatment, they promote M1 polarization to enhance anti-tumor immunity; in cardiovascular and respiratory diseases, they induce M2 polarization to accelerate tissue repair; and in diabetes, they modulate the M1/M2 balance to improve insulin sensitivity and facilitate wound healing." (PMID 41181144, 2025). "By enhancing insulin secretion, A. muciniphila could help regulate blood glucose levels more effectively, offering a natural approach to diabetes and related disorder management." (PMID 40806100, 2025). "Diabetes is a chronic metabolic disorder characterized by elevated blood glucose levels, resulting from either insufficient insulin production by the pancreas or ineffective use of insulin by the body." (PMID 40285071, 2025). "Optimal diabetes management is achieved through intensive glycemic control, which includes frequent blood glucose monitoring using sensors, accurate insulin administration via injections or insulin pumps, and adherence to a structured regimen of diet and physical activity." (PMID 40004164, 2025). "In patients with diabetes mellitus, physical activity may improve insulin sensitivity and glucose metabolism." (PMID 40565151, 2025). "Other diabetes treatments included liraglutide (26%), dipeptidyl peptidase-4 inhibitors (15%), sulfonylurea (18%), sodium-glucose transport inhibitor (SGLT2i) (9%), and insulin (39%)." (PMID 40155929, 2025). "In addition, it is crucial to conduct a training program for diabetes patients on insulin therapy to enhance their knowledge and self‐administration skills." (PMID 40226177, 2025). "Insulin-sensitizing therapies for diabetic wounds are a multifaceted approach aimed at addressing the challenges of impaired wound healing in individuals with diabetes." (PMID 40280905, 2025). "The extent and nature of these complications depend on several factors, including whether the diabetes is pregestational or gestational, the degree of maternal glycemic control, and whether the mother requires insulin therapy." (PMID 41185740, 2025). "Overall, we identified that higher fiber higher carbohydrate intakes are likely beneficial to patients with diabetes when compared with lower carbohydrate lower fiber diets through the reduction of HbA1c, fasting insulin, total cholesterol, and LDL cholesterol." (PMID 39295498, 2025). "Among the different types of diabetes, type 1 diabetes, caused by a lack of insulin secretion, is particularly challenging to treat." (PMID 40807812, 2025). "This retrospective, observational study is aimed at analyzing real‐world data (RWD) from a digital device (ESYSTA, Emperra GmbH E‐Health Technologies, Germany) that incorporates both CGM and BGM data to enhance the glycemic control and self‐management of insulin‐treated people with diabetes." (PMID 41497476, 2025). "Currently, insulin and oral hypoglycemic medications are the leading therapies for diabetes." (PMID 40063647, 2025). "Conversely, low weight loss, the use of insulin and poorly controlled T2D (HbA1c > 7 %) are negative predictors of diabetes remission." (PMID 40740163, 2025). "For example, in FGDs with adults, they said that diabetes as a chronic condition, characterized by elevated blood sugar levels, is also genetic, lifestyle, and diet and it primarily results from the body’s inability to produce or use insulin effectively." (PMID 41490310, 2025).